TG (thyroglobulin)
Diseases named in the same sentence as TG in open-access papers (continued):
Sharing a sentence is not in itself a finding about the gene and the disease.
tumor (continued). "In the present case study, immunohistochemistry revealed that tumor cells exhibited positive staining for CEA and were negative for thyroglobulin and TTF-1." (PMID 23760305, 2013). "Immunohistochemical studies revealed that tumor cells were strongly immunoreactive for PTH and negative for calcitonin, TTF-1, and thyroglobulin, thus confirming that the tumor cells were parathyroid in origin." (PMID 23936709, 2013). "CD10, vimentin and pancytokeratin positivity, however, in the same tumour areas cells were negative with TTF-1, thyroglobulin and calcitonin." (PMID 22933935, 2011). "Cox proportional hazards models were used to assess predictors (gender, age, ethnicity, tumor size, surgical histology) of WDTC persistence/recurrence (elevated thyroglobulin levels with negative thyroglobulin-antibodies; or positive imaging)." (PMID 21496269, 2011). "In this case, the tumour showed diffuse positivity with antibodies to EMA, CAM 5.2, CK7, CK19 and TTF-1 and no expression (negative) with CK 20, CEA, S-100 protein, thyroglobulin, SMA and p63." (PMID 18492272, 2008). "Tumor markers specific to TDCC have not been established, although elevated thyroglobulin levels in blood or cysts may indicate malignancy." (PMID 40347268, 2025). "Singh K showed that the tumor cells are positive for calcitonin, HMB-45, carcinoembryonic antigen (CEA), syn, chromogranin, vimentin, and epithelial membrane antigen and negative for TG, S-100, melan A, and TTF-1." (PMID 30424779, 2018). "Interestingly, the tumor contained a 3 mm focus of a lesion staining positive for Thyroid Transcription Factor-1 (TTF1), Thyroglobulin, and was negative for RCC marker." (PMID 28249616, 2017). "Tumor cells were positive for CK7 EMA, CKAE1/AE3, CD15, CA-125, while immunoreaction for Calretinin, WT1, estrogen, and progesterone receptors, cytokeratin 20, CD10, alpha fetoprotein, CDX2, TTF1, and thyroglobulin were all negative." (PMID 27912770, 2016). "The tumor cells were positive for TTF-1, PAX8, Napsin-A and were negative for thyroglobulin." (PMID 27774331, 2016). "The tumor cells were negative for TTF-1, thyroglobulin, CD10, WT-1, SMMHC, CEA, and S-100." (PMID 25133003, 2014). "TTF-1, thyroglobulin, calcitonin, CK20 and CK7 were negative in metastatic tumour areas." (PMID 22933935, 2011). "In the cases investigated, several neoplasms, previously diagnosed as ccRCC, showed a thyroid-like aspect, characterised by an eosinophilic content cystic-follicular architecture, with negativity for TTF-1 and thyroglobulin and without, as already mentioned, a specific immunohistochemical pattern." (PMID 36611378, 2022). "While tumour weights and volumes were not significantly higher in LAM1:PIK3CAE545K mice, there was a decrease in expression of thyroid differentiation markers TTF-1, thyroglobulin, PAX8 and B-catenin, suggesting that introduction of PIK3CAE545K led to dedifferentiation in vivo." (PMID 35193694, 2022). "Most tumor cells of the neuroendocrine component were immunoreactive for CAM.5.2, cytokeratin (CK) 7, CK AE1/AE3, synaptophysin, chromogranin A, parathormone, GATA3, and parafibromin, whilst they were negative for thyroglobulin, TTF1, calcitonin, glucagon, and S100." (PMID 32506375, 2021).
cancer (110 papers, 1966 to 2025). A tumor composed of atypical neoplastic, often pleomorphic cells that invade other tissues. "In this study, we discovered a novel, functional microRNA encoded within the thyroglobulin gene, whose downregulation in cancer leads to deregulation of pathways related to MAP kinase signaling." (PMID 28855631, 2017). "However, preoperative thyroglobulin measurement is generally not recommended when the thyroid gland is intact, as circulating thyroglobulin can originate from both benign thyroid tissue and carcinoma, limiting its diagnostic specificity." (PMID 40746588, 2025). "However, G0F:G1F is distinct from thyroglobulin, so may address limitations of thyroglobulin, such as patients with thyroglobulin antibody, patients receiving thyroid hormone, or to predict risk of cancer recurrence prior to recurrence." (PMID 36437732, 2023). "Therefore, the elevation of serum thyroglobulin in HT could be due to increased leak in response to TSH stimulation or the excessive production by the associated cancer." (PMID 23522401, 2013). "Several sialylated proteins, such as PSA, CA125, and THYROGLOBULIN, are already used clinically to monitor cancer progression and recurrence." (PMID 39937175, 2025). "These cancers are characterized by their ability to maintain some degree of normal thyroid cell function, including iodine uptake and thyroglobulin (Tg) production." (PMID 40104303, 2025). "Abnormal sialylation has been linked to malignant transformation, and several sialylated glycoproteins, including prostate-specific antigen (PSA), cancer antigen 125 (CA125), and thyroglobulin, are utilized as clinical cancer biomarkers." (PMID 39937175, 2025). "According to our study, MPN patients were diagnosed at an older age, displayed an elevated body mass index, and presented with increased thyroglobulin antibody levels, along with a more pronounced familial history of cancer." (PMID 38894738, 2024). "Metastatic cancer cells are able to synthesize thyroglobulin but they lack an intact follicular structure." (PMID 38027220, 2023). "Urinary exosomal thyroglobulin showed an increasing trend in post-operative patients as compared to serum thyroglobulin, suggesting the probable recurrence of cancer." (PMID 36766698, 2023). "Among patients with high serum concentrations of thyroglobulin (>200 ng/mL), the ratios were significantly lower in those with cancer compared to those with benign nodules." (PMID 35406382, 2022). "There was one case (4.2%) of biochemical (rising serum thyroglobulin) cancer persistence/recurrence in a woman with cancer initially classified as intermediate risk (T1bN1bM0)." (PMID 35108218, 2022). "Serum thyroglobulin (Tg) and anti-thyroglobulin antibody (TgAb) levels are recommended for assessing residual or recurrent diseases because the well-differential cancer or thyroid follicular cells are the only sources of serum Tg." (PMID 33482804, 2021). "The remaining 2/13 patients had multifocal carcinomas with thyroglobulin levels undetectable (case n." (PMID 34441438, 2021). "Some studies suggest that radio-iodinated thyroglobulin released from functioning cancer tissue is metabolized in liver and results in visualization of liver." (PMID 31049077, 2019). "Patients who were treated with RAI following rhTSH stimulation, patients who presented positive anti-thyroglobulin antibodies, and patients who had micro-cancers were excluded." (PMID 31425569, 2019). "It is well known that the main factors affecting the thyroglobulin level include the amount of residual thyroid tissue or cancer lesion, TSH level, the time after the operation, and the thyroid hormone withdrawal time." (PMID 30619772, 2018). "The three main arguments in favor of total thyroidectomy are the ability to perform RAI, the use of thyroglobulin as a follow-up marker, and the high rate of contralateral carcinomas." (PMID 27013326, 2016).
cancer (continued). "One of those previous studies showed that patients with PET-positive lesions were also older, had a higher initial cancer stage and higher thyroglobulin levels." (PMID 22985118, 2012). "Matsuda and colleagues have reported that malignant SO can be diagnosed before operation by the evaluation of free T3, and T4, Thyroglobulin, and TSH." (PMID 22613573, 2012). "One aim of this therapy is to destroy thyroid remnant to remove their competition with cancer cells for secretion of thyroglobulin or 131I uptake." (PMID 21040579, 2010). "It is well established that thyroglobulin plays a reliable role in the monitoring of the well-differentiated carcinoma course, after total thyroidectomy." (PMID 19578508, 2008). "In all patients with HGFDTC, serum thyroglobulin may not serve as an accurate marker of disease recurrence, as such cancers secrete less thyroglobulin, due to their cell poor differentiation." (PMID 39458070, 2024). "Iodine-131 (RAI therapy), a metabolic radiotherapeutic intervention, may be used to target the carcinoma component, although its efficacy against the mesenchymal component remains limited as it lacks thyroglobulin expression." (PMID 39436475, 2024). "A retrospective study on cancer patients under PD1 Ab therapy (nivolumab, pembrolizumab) associated elevated blood levels of thyroid-stimulating hormone (TSH) and thyroglobulin Ab with early onset of IRAE and prolonged survival, proposing IRAE as predictive markers for clinical outcome." (PMID 37686465, 2023). "Redifferentiation therapy is the reprogramming of the cancer differentiation state and increasing the response of cancer cells to radioiodine therapy by promoting the expression of genes required for iodine uptake and thyroglobulin in TC cells." (PMID 36523971, 2022). "Other 5/13 patients had unifocal carcinomas, 1/5 with thyroglobulin undetectable (case n." (PMID 34441438, 2021). "A cancer panel was designed in-house based on data published previously to analyze the noncoding regions of six genes—surfactant protein A1, B, and C, as well as albumin, lipase, and thyroglobulin." (PMID 30999697, 2019). "In patients without thyroid remnant, radioiodinated thyroglobulin released from functioning cancer tissue is regarded as the cause of diffuse hepatic uptake of radioiodine." (PMID 26181567, 2015). "Preferentially methylated cancer also tended to have larger tumors and higher thyroglobulin levels, which might relate to cancer progression." (PMID 24367375, 2013). "Using statistical analysis of whole-genome sequences across a diverse collection of cancers, they determined that other tumor types harbor similarly prevalent hotspots of noncoding somatic indel mutations, targeting lineage-defining genes (i.e., ALB, TG, and LIPF)." (PMID 30999697, 2019). "After successful thyroid remnant ablation thyroglobulin may be secreted by only cancer cells." (PMID 21040579, 2010). "We identified five genes (KCNJ16, SLC26A4, TG, TPO, and SYT1) as potential cancer treatment targets." (PMID 37208644, 2023). "Immunophenotypically, the carcinoma was consistent with thyrocyte differentiation with expression of monoclonal PAX8, TTF1, and thyroglobulin (the last predominantly in extracellular colloid)." (PMID 34997561, 2022). "Differentiation of BRAF FOXE1+/+ and BRAF FOXE1+/− cancers was analyzed by IHC for two representative differentiated thyroid markers, the transcription factor PAX8, and the precursor of thyroid hormones thyroglobulin (TG)." (PMID 33375029, 2020). "Traditional arguments for adhering to total thyroidectomy are the presence of contralateral carcinomas, the ability to perform RAI and the use of thyroglobulin as a follow-up marker." (PMID 27013326, 2016). "Measurement of serum thyroglobulin (Tg) levels after TSH stimulation (stimulated Tg [s-Tg]) may help assess disease persistence or presence of thyroid remnant and predict potential cancer recurrence." (PMID 38578436, 2024).
cancer (continued). "Thyroglobulin was not elevated above the upper limit of the reference range in patients with cancer." (PMID 38501028, 2024). "One of the main problems of follow up in patients with this type of cancer, is the need for thyroglobulin stimulation, not to mention the poor availability of 123I or 124I, to perform studies with a higher degree of sensitivity." (PMID 35002972, 2021). "Stemness markers as CD133, CD44, Oct-4, Sox-2, and Nanog were revealed in both normal and cancer thyrospheres; conversely, thyroid differentiation markers [thyroperoxidase (TPO), thyroglobulin (Tg), thyroid-stimulating hormone receptor (TSH-R)] were detected at low levels in both cellular types." (PMID 32982967, 2020). "Furthermore, TG staining revealed that the differentiated cells retain thyroglobulin in the cytoplasm in both FOXE1+/+ and FOXE1+/− cancers." (PMID 33375029, 2020). "Our driver selection method successfully identified 116 probable novel cancer-causing genes, with 4 discovered in patients having no alterations in any known driver genes: MXRA5, OBSCN, RYR1, and TG." (PMID 33232371, 2020). "18FDG-PET CTs are also used in those patients whose cancers are very poorly differentiated and make no thyroglobulin." (PMID 22530159, 2012). "Furthermore, in keeping with other thyroid PSCC cases in the literature, a negative TTF-1 and thyroglobulin helps to support the diagnosis of PSCC by excluding a cancer arising from follicular thyroid cells." (PMID 24942336, 2014). "PTH, GCM2, SYN, CgA, GATA3, and CAM5.2 are always positive in cancer cells, while TTF1, PAX8, CAL, and TG are always negative." (PMID 38019325, 2023). "Immunohistochemical analyses of the cancer cell line (passage number 23) also showed ALK expression (ALK-positive) and confirmed thyroidal origin (TTF1 positive, PAX8 positive, thyroglobulin negative)." (PMID 33878728, 2021). "ROC Curve Analysis demonstrated that a preoperative thyroglobulin level of 31.3 mcg/L had a sensitivity of 75% and a specificity of 62.5% to differentiate NIFTP from non-NIFTP cancers." (PMID 31898554, 2020). "A biopsy confirmed carcinoma, positive for thyroid transforming factor-1 and AE1/AE3 but negative for p40 and thyroglobulin, which is consistent with the carcinoma of lung origin." (PMID 31145296, 2019). "Poorly differentiated or undifferentiated carcinomas no longer express mature thyroid-specific genes including sodium iodide symporter (NIS), thyroperoxidase (TPO), thyroglobulin (TG), and thyrotropin-stimulating hormone receptor (TSHR)." (PMID 18682709, 2008). "Although these cancer cell lines also express TSHR and the thyroid transcription factor Pax8, other markers of terminally differentiated thyroid cells, such as the sodium-iodide symporter and thyroglobulin, are not expressed in these cell lines (Friedman and Lin, unpublished observations)." (PMID 19404394, 2009).
infection (16 papers, 2018 to 2026). The state of being infected such as from the introduction of a foreign agent such as serum, vaccine, antigenic substance or organism. "Thyroid function was assessed by profiling serum TSH, free T3, and free T4; iodine status was estimated using serum thyroglobulin level, while infection status was determined by measuring anti-SARS-CoV-2 antibody against the nucleocapsid antigen." (PMID 36399104, 2022). "Mouse sera were collected 4–6 weeks following i.p. infection and tested for reactivity against dsDNA, thyroglobulin, and IgG." (PMID 29973931, 2018).
immune disease (6 papers, 2014 to 2025). "Immune disorders lead to reactivity to thyroid autoantigens such as thyroid peroxidase (TPO), thyroglobulin (TG), and thyroid-stimulating hormone receptor." (PMID 36362236, 2022). "Also one patient had anti-dsDNA, one had P-ANCA, and two had anti-TPO and anti-TG positivity, with normal thyroid function tests no auto-immune diseases." (PMID 25878633, 2015).
neurological disease (6 papers, 2014 to 2024). "In our case-control study, levels of free thyroxine (FT4), total triiodothyronine (TT3), total thyroxine (TT4), and anti-thyroglobulin antibodies (TG-Ab) were notably reduced among individuals with neurological disorders, compared with healthy controls (P<0.001, P<0.001, P=0.036, P=0.006)." (PMID 39717108, 2024).
adenocarcinoma (4 papers, 2013 to 2021). A common cancer characterized by the presence of malignant glandular cells. "Cells of the adenocarcinoma component were CAM.5.2, CK7, CK AE1/AE3, and GATA-3 positive and negative for synaptophysin, chromogranin A, parathormone, parafibromin, thyroglobulin, TTF1, calcitonin, glucagon, S100, PGP-9 and Bcl-2." (PMID 32506375, 2021). "The histology analysis of the biopsy and surgical specimen favored an adenocarcinoma with immunostaining positive for TTF1 and thyroglobulin (Tg)." (PMID 23509641, 2013).
genetic disease (3 papers, 2012 to 2024). "In addition, other genetic disorders may be more effective than TPO mutations in CH patients with dyshormonogenesis including the sodium symporter (NIS) gene, the pendrin gene (PDS), the thyroid oxidase gene 2 (THOX2 or DUOX2), and thyroglobulin gene." (PMID 22919382, 2012).
TG also shares sentences with these, for which no sentence is quoted: dyslipidemia (42 papers); endocrine disorder (25); cardiovascular disease (21); metabolic disorders (21); osteoporosis (11); dementia (10); papillary carcinoma (10); Sepsis (10); bipolar disorder (9); euthyroid sick syndrome (9); fatty liver disease (9); atrial fibrillation (8); glioma (8); Infertility (8); malnutrition (8); myocardial infarction (8); heart failure (7); mood disorder (7); Addison’s disease (6); adenoma (6); atherosclerosis (6); colorectal cancer (6); Hypoglycemia (6); iron deficiency (6); neuropathy (6); Zinc deficiency (6); Alzheimer disease (5); cardiac hypertrophy (5); coronary artery disease (5); hepatocellular carcinoma (5).
A further 345 diseases each share a sentence with TG in 5 papers or fewer.